HPN (hepsin)
Description:
Serine protease that cleaves extracellular substrates, and contributes to the proteolytic processing of growth factors, such as HGF and MST1/HGFL. Plays a role in cell growth and maintenance of cell morphology. Plays a role in the proteolytic processing of ACE2. Mediates the proteolytic cleavage of urinary UMOD that is required for UMOD polymerization.
Synonyms: TMPRSS1
Tractability: Small molecule: a structure with a bound ligand is known; a high-quality ligand is known. Antibody: UniProt places it where antibodies can reach, with high confidence; its Gene Ontology location is reachable by antibodies, with high confidence; UniProt predicts a signal peptide or a membrane-spanning region. PROTAC: ubiquitination databases record sites on it; a small molecule that binds it is known.
Target class: Enzyme; Protease; Serine protease
Gene: Protein-coding gene on chromosome 19 (35,040,506 to 35,066,592, forward strand). Ensembl gene ENSG00000105707.
Subcellular location: Cell membrane; Apical cell membrane
Pathways (Reactome):
Signal Transduction: MET Receptor Activation; Signaling by MST1
Gene Ontology:
Molecular function: peptidase activity; protein binding; serine-type endopeptidase activity; serine-type peptidase activity; serine-type exopeptidase activity
Biological process: basement membrane disassembly; host-mediated activation of viral transcription; negative regulation of apoptotic process; negative regulation of epithelial cell proliferation; negative regulation of epithelial to mesenchymal transition; positive regulation of cell growth; positive regulation of hepatocyte proliferation; positive regulation of plasminogen activation; proteolysis; regulation of cell shape; cochlea morphogenesis; detection of mechanical stimulus involved in sensory perception of sound; pilomotor reflex; positive regulation of gene expression; positive regulation of thyroid hormone generation; potassium ion transmembrane transport; protein processing; response to thyroid hormone
Cellular component: apical plasma membrane; cell surface; endoplasmic reticulum membrane; extracellular exosome; membrane; nuclear membrane; plasma membrane; cell-cell junction; neuronal cell body
Genetic constraint (gnomAD): Loss-of-function variants: 13 observed, 52.19 expected, observed/expected ratio (o/e) 0.25, 90% interval 0.16 to 0.4. The upper end of that interval is the gene's LOEUF score, 0.4, which puts it in group 1 of 6, group 1 being the genes least tolerant of losing a copy. Missense variants: 451 observed, 560.9 expected, observed/expected ratio (o/e) 0.8, 90% interval 0.74 to 0.87. Synonymous variants: 225 observed, 235.13 expected, observed/expected ratio (o/e) 0.96, 90% interval 0.86 to 1.07.
Homologues: Orthologues: chimpanzee HPN (100% identical), macaque HPN (99% identical), dog HPN (95% identical), pig HPN (92% identical), rabbit HPN (92% identical), guinea pig HPN (88% identical), mouse Hpn (88% identical), rat Hpn (86% identical), tropical clawed frog hpn (63% identical), zebrafish hpn (51% identical), Drosophila melanogaster Sb (30% identical), zebrafish tmprss12 (24% identical), and 1 more. Paralogues in human: TMPRSS3 (32% identical), TMPRSS11D (30% identical), TMPRSS6 (30% identical), ST14 (30% identical), TMPRSS13 (30% identical), TMPRSS15 (30% identical), TMPRSS11F (29% identical), TMPRSS2 (29% identical), TMPRSS11A (29% identical), TMPRSS9 (29% identical), TMPRSS11B (28% identical), TMPRSS5 (28% identical), and 5 more.
Diseases named in the same sentence as HPN in open-access papers:
HPN is named in the same sentence as 67 diseases in open-access papers, as found by Europe PMC text mining. Sharing a sentence is not in itself a finding about the gene and the disease. The quoted sentences say what the papers report.
prostate carcinoma (57 papers, 2004 to 2025). A carcinoma that arises from epithelial cells of the prostate gland. "HPN encodes a type II transmembrane serine protease associated with the growth and progression of cancers, particularly prostate cancer." (PMID 39595075, 2024). "Another protein-coding gene widely associated with prostate cancer is hepsin (official symbol HPN), which was reported as differentially expressed in 33 US patients and 67 patients from the UK." (PMID 39595075, 2024). "In our study, we identified AOX1, APOC1, ARMCX1, FLRT3, GSTM2, and HPN as biomarkers associated with prostate cancer (PCa)." (PMID 37583929, 2023). "Apc loss has also been shown to cooperate with hepsin overexpression or Smad4 loss to promote invasive prostate cancer, further indicating that invasive progression in Apc-deficient prostate cancer requires an additional genetic alteration." (PMID 35204808, 2022). "Among them, 18 patients showed biochemical recurrence, suggesting the diagnostic potential of circulating hepsin in prostate cancer." (PMID 35204704, 2022). "One of the plausible explanations was that overexpression of HPN was associated with matrix degradation (invasion and metastasis initiator), similar to that of prostate cancer." (PMID 32630086, 2020). "The serine protease hepsin is frequently overexpressed in human prostate cancer (PCa) and is associated with matrix degradation and PCa progression in mice." (PMID 31399560, 2019). "The research has proved that expression of the encoded protein of HPN is related to the growth and progression of cancers, particularly prostate cancer." (PMID 30158596, 2018). "These include KLK12 (log2FC 3.2 iCluster3) and HPN (log2FC 1.6–2.2), which have both been linked with prostate cancer aggressiveness." (PMID 26501111, 2015). "It has been reported that hepsin, a cell surface protease is associated with growth and progression of cancers, particularly prostate cancer and its over-expression is found in more than 90% of human prostate cancer cases." (PMID 24596579, 2014). "Hepsin is prominently overexpressed in the majority of human prostate cancers and functional in vivo studies support a causal role for Hepsin in cancer progression." (PMID 24657880, 2014). "STAT6 has been recently linked to HPN as one of the most robust pair of biomarkers for prostate cancer using an integrative approach that linked several microarray datasets." (PMID 20805891, 2010). "Another case–control association study on hepsin variants and prostate cancer in a European ancestry cohort (590 cases and 576 controls) also showed significant allele frequency differences between cases and controls at five SNPs that are located contiguously within the hepsin gene." (PMID 35204704, 2022). "Moreover, a major 11-locus haplotype is significantly associated with prostate cancer susceptibility, and one of the SNPs is associated with the Gleason score, showing the role of hepsin in tumor aggressiveness." (PMID 35204704, 2022). "Moreover, genomic amplifications of hepsin were significantly associated with prostate cancer metastasis." (PMID 35204704, 2022). "In addition, the overexpression of hepsin in prostate cancer tissues is associated with a shorter survival time." (PMID 35204704, 2022). "They suggested that decreased hepsin expression could be linked with poor prostate cancer prognosis as exogenously provided hepsin negatively regulated the growth of metastatic prostate cancer cells." (PMID 26014348, 2015). "It is based on hepsin activity determination in epithelial cells of the prostate collected with urine after rectal massage (Patent “Prostate cancer detection test-kit and prostate cancer diagnostic method” [Eurasian patent No011694], diagnostic kit (Registration No FSR 2009/05065))." (PMID 22649671, 2011). "However, recent data from microarray profiling studies have linked hepsin with prostate cancer pathogenesis." (PMID 15928670, 2005).
prostate carcinoma (continued). "A novel peptide with high specificity and sensitivity toward hepsin, an emerging marker of prostate cancer, has been applied to improve pharmacokinetics and enhance cancer detection." (PMID 41008874, 2025). "Additional examples are the CV-1 peptide targeting CD44 in gastric tumors, plectin-1 targeted peptides for pancreatic ductal adenocarcinoma (PDAC), and hepsin-specific peptides for prostate cancer imaging and detection." (PMID 41008874, 2025). "The possible prostate cancer (PCa) diagnostic biomarkers AOX1, APOC1, ARMCX1, FLRT3, GSTM2, and HPN were identified and validated using the GSE69223 and GSE71016 datasets." (PMID 37583929, 2023). "This is in line with findings in other pathologies, such as prostate cancer, in which hepsin proteolyzes laminin-332, a cell matrix molecule necessary for cell-to-cell adhesion, thereby enhancing tumor cell invasion." (PMID 37275957, 2023). "Previous studies have shown the overexpression of hepsin in prostate cancer, and the dysregulation of hepsin promotes cancer cell proliferation, migration, and metastasis in vitro and in vivo." (PMID 35204704, 2022). "It is notable that hepsin expression in prostate cancer was the most significantly increased (492 cases of prostate cancer compared to 152 normal)." (PMID 35204704, 2022). "The review incorporated with our work showed that hepsin expression levels were specifically increased in prostate cancer, and higher expression in metastatic tumors than in primary tumors was also observed." (PMID 35204704, 2022). "Since hepsin is specifically and significantly upregulated in prostate cancer tissues and metastatic cancer, it was anticipated to be a biomarker suitable for prostate cancer screening, diagnosis, or monitoring tumor progression using liquid biopsies." (PMID 35204704, 2022). "Using in silico protein–protein interaction prediction, mechanistic analysis showed that hepsin interacted with eight other oncogenic proteins, whose expression was significantly correlated with hepsin expression in prostate cancer." (PMID 35204704, 2022). "An example of a utility-dependent tumor expression of HPN occurs in prostate cancer, where this “HPN paradox” was described." (PMID 35804878, 2022). "Consistent with the hepsin expression levels in prostate cancer, these genes’ expression levels were also significantly increased in cancer tissues in comparison with normal prostate tissues." (PMID 35204704, 2022). "Several strategies for targeting hepsin have been developed, such as hepsin-specific inhibitors and antibodies, exhibiting preventive functions in reversing hepsin’s oncogenic functions in prostate cancer." (PMID 35204704, 2022). "An in vitro study showed that hepsin-cleaved laminin-332 enhanced the motility of DU145 prostate cancer cells." (PMID 35204704, 2022). "Hepsin was upregulated in breast, ovarian, and prostate cancers, thymoma, uterine corpus endometrial carcinoma, and uterine carcinosarcoma, in comparison with associated normal tissues." (PMID 35204704, 2022). "Their expression levels were positively correlated with hepsin in prostate cancers according to an analysis of Taylor’s dataset." (PMID 35204704, 2022). "In recent years, a type II transmembrane serine protease called hepsin has attracted attention due to its overexpression and oncogenic functions in prostate cancer." (PMID 35204704, 2022). "Similar to the early antigens identified for breast and colon cancer, silencing gene expression of either HPN or AMACR significantly inhibits prostate cancer cell growth." (PMID 35948756, 2022). "Hepsin is specifically overexpressed in prostate cancer, and several studies have shown that the expression levels are even higher in metastatic tumors than primary tumors." (PMID 35204704, 2022). "Both in vitro and in vivo studies have demonstrated oncogenic functions of hepsin in prostate cancer, such as promoting cell growth, cell proliferation, invasion, migration, and metastasis." (PMID 35204704, 2022).
prostate carcinoma (continued). "In vitro cell binding study and in vivo characterization of the radioligand in mice, implanted with two prostate cancer cell lines displaying varying levels of hepsin, showed that [64Cu]3B exhibits desirable characteristics for PET imaging of hepsin." (PMID 36145330, 2022). "This protein causes disorganization of basement membrane to promote progression of metastasis in a mouse prostate cancer model whereas targeted inhibition of hepsin blocks prostate cancer bone metastasis." (PMID 29254206, 2017). "For example, overexpression of the HEPSIN oncogene in prostate cancer downregulates the expression and IRES activity of UNR." (PMID 28763470, 2017). "The role of hepsin in cancer growth remains controversial; hepsin is required for hepatoma cell growth, whereas it reportedly inhibits the growth of prostate cancer cells." (PMID 27385093, 2016). "The contribution of hepsin in the development of secondary liver tumours is confirmed by the results of studies conducted on prostate cancer models." (PMID 25598217, 2015). "Hepsin upregulation in the context of the prostate gland in vivo promotes SV40 large T antigen-driven prostate cancer progression and metastasis to the liver, lung and bone." (PMID 24657880, 2014). "For this purpose, we chose to use LPB-Tag/PB-Hepsin mice, which is the only existing genetic model of metastatic prostate cancer that expresses Hepsin and consistently shows bone metastasis, which is prevalent in human prostate cancer." (PMID 24657880, 2014). "Overall, we conclude that HepIn-13 displays dose-dependent inhibition of Hepsin overexpression-relevant prostate cancer phenotypes in LPB-Tag/PB-Hepsin mice and blocks prostate cancer metastasis in this animal model." (PMID 24657880, 2014). "Hepsin increases early in prostate cancer initiation and its high levels are maintained throughout progression and metastasis." (PMID 24657880, 2014). "IPL has the ability to bind a type II transmembrane serine protease called hepsin (HPN), which is uniquely expressed in prostate cancer cells." (PMID 25988156, 2014). "While HepIn-13 is the first small molecule Hepsin inhibitor used in an animal model of prostate cancer, a protein-based Hepsin inhibitor, Kunitz domain-1, was previously used in a xenograft model of prostate cancer." (PMID 24657880, 2014). "Hepsin (HPN) is one of the most upregulated genes in human prostate cancer and is overexpressed in up to 90% of prostate tumors with levels often increased >10 fold." (PMID 24657880, 2014). "Additional Hepsin overexpressing models of prostate cancer will need to be developed to analyze the efficacy of HepIn-13." (PMID 24657880, 2014). "Expression of hepsin protein in prostate cancer has been found by cDNA microarrays to correlate inversely with patient prognosis." (PMID 24282788, 2013). "For this purpose, the well-known prostate cancer markers Hepsin and AMACR have been tested as positive controls." (PMID 21829708, 2011). "Hepsin is widely reported to be highly over-expressed in more than 90% of human prostate tumors, making it a significant marker and a target for prostate cancer." (PMID 19874631, 2009). "The CD26+ cancer cells also had elevated expression of prostate cancer-associated genes AMACR (α-methylacyl-CoA racemase), HPN (hepsin) and PCA3 (prostate cancer antigen 3)." (PMID 20021671, 2009). "In particular, hepsin, which has the highest depended degree, has been reported to have significant involvement in the pathogenesis of prostate cancer." (PMID 19874631, 2009). "The mean fold difference for hepsin expression between prostate cancer and benign cells was 5.7 (p = 0.00004) for unamplified samples, 4.4 (p = 0.0003) after linear amplification, and 4.3 (p = 0.00003) as determined by microarray analysis." (PMID 17376245, 2007). "Both AMACR and hepsin were upregulated in prostate cancer compared to benign prostatic epithelial cells." (PMID 17376245, 2007).
prostate carcinoma (continued). "HPN is a serine protease that has been shown to be overexpressed in prostate cancer cells, and significantly correlates with poor clinical outcome." (PMID 14760385, 2004). "For prostate cancer individual gene expression, the two axes for discriminating tissue types are: 1) Human hepatoma mRNA for serine protease hepsin and 2) Human adipsin." (PMID 15469618, 2004). "For prostate cancer single gene expression, the two axes for discriminating tissues are: 1) Human hepatoma mRNA for serine protease hepsin, and 2) Human adipsin." (PMID 15469618, 2004). "Hepsin, a prostate cancer serum biomarker, while marginally overexpressed in primary, was further overexpressed in secondary ovarian cancer tissue." (PMID 14760385, 2004). "TEPSIN Adaptor Related Protein Complex 4 Accessory Protein (TEPSIN) is a membrane serine protease expressed in a variety of human tissues including kidney, prostate and thyroid, precise control of Hepsin proteolytic activity is an effective treatment for prostate cancer." (PMID 36713456, 2022). "For instance, a treatment with the hepsin inhibitor Kunitz domain-1 of prostate cancer DU145 cells could suppress cancer cell motility and further inhibit cancer cell progression and metastasis." (PMID 35204704, 2022). "The direct cleavage of laminin-332 may be one mechanism by which hepsin promotes prostate cancer progression and metastasis, possibly by upregulating prostate cancer cell motility." (PMID 35204704, 2022). "The significant increase in hepsin in prostate cancer was also observed in other studies." (PMID 35204704, 2022). "Thus, in prostate cancer, HPN has a clear pro-tumorigenic function by promoting invasion processes in certain settings." (PMID 35804878, 2022). "However, HGF expression is reduced in prostate cancer, compared to in normal tissues, and is negatively correlated with hepsin in prostate cancer." (PMID 35204704, 2022). "Moreover, we have identified that TMEFF2 is also a novel substrate for other proteases implicated in prostate cancer, including two ADAMs (ADAM9 and ADAM12) and the type II transmembrane serine proteinases (TTSPs) matriptase‐1 and hepsin." (PMID 28762604, 2018). "Interestingly, overexpression of HEPSIN, one of the most consistently up-regulated genes in prostate-cancer patients, inhibits the expression and IRES activity of UNR in cancer-derived cell lines." (PMID 28763470, 2017). "The strongest hepsin staining was in the precursor lesions of prostate cancer (HG-PIN)." (PMID 26014348, 2015). "Supporting our results, Vasioukhin hypothesized that hepsin may promote metastasis in prostate cancer." (PMID 26014348, 2015). "Therefore, different approach to drive Hepsin expression will have to be used in the future to generate new models to analyze the efficacy of HepIn-13 in inhibition of prostate cancer bone metastasis." (PMID 24657880, 2014). "We hypothesized that inhibition of Hepsin activity using small molecules would attenuate prostate cancer progression and may have therapeutic potential in other cancers with Hepsin amplification." (PMID 24657880, 2014). "We show here that HepIn-13 inhibits Hepsin and blocks prostate cancer metastasis." (PMID 24657880, 2014). "Treatment of LPB-Tag/PB-Hepsin mice with Hepsin inhibitor HepIn-13 completely suppressed the development of bone metastasis, strongly suggesting that Hepsin plays an important role in the skeletal spread of prostate cancer." (PMID 24657880, 2014). "This Hepsin activity is likely to be important for prostate cancer progression, because HGF/MET signaling pathway is strongly implicated in tumor progression and metastasis in prostate cancer." (PMID 24657880, 2014). "While Hepsin antibodies are likely to be useful for prostate cancer imaging, the therapeutic use of these antibodies for tumor eradication may be somewhat limited due to the prominent expression of endogenous Hepsin in hepatocytes." (PMID 24657880, 2014).